HIF1A (hypoxia inducible factor 1 subunit alpha)
Diseases named in the same sentence as HIF1A in open-access papers (continued):
Sharing a sentence is not in itself a finding about the gene and the disease.
tumor (continued). "Consequently, YY1/HIF-1a upregulates VEGF expression and drives tumor vascularization to augment oxygen and nutrient perfusion." (PMID 40867514, 2025). "In contrast, UBE2V1 overexpression significantly increased tumor growth, while systemic administration of PX-478 suppressed tumor development in a dose-dependent manner, confirming that the pro-tumorigenic effects of UBE2V1 in HCC are mediated through HIF-1α activation." (PMID 41446875, 2025). "Notably, HIF-1α primarily regulates genes involved in anaerobic glycolysis and cell death, while HIF-2α controls genes related to erythropoietin (EPO) synthesis and tumor stemness or pluripotency." (PMID 40813760, 2025). "Notably, the expression level of HIF-1α protein in GBM significantly surpasses that in normal brain tissue, closely correlating with the tumor's malignant behavior." (PMID 39781344, 2025). "Moreover, the RT-qPCR and western blotting results also indicated that HIF1α, HIF2α, CD133, and CD15 were highly expressed in mouse tumor tissues under normoxia, while they were rarely or were less expressed in tumor tissues exposed to HBO." (PMID 40370575, 2025). "ESM1 promotes angiogenesis and tumor progression in CRC through activation of the PI3K/Akt/mTOR signaling pathway and upregulation of pro-angiogenic and inflammatory factors such as VEGF, COX-2, and HIF-1α." (PMID 40722723, 2025). "Additionally, erinacine S treatment correlated with decreased expressions of p-AKT, p-ERK, HIF1α, PCNA, and NFκB p50 in the tumor region of the HCT-116/FUR xenograft in nude mice." (PMID 41209562, 2025). "This study identifies CD73 (NT5E) as a direct hypoxia-responsive effector of HIF1α and demonstrates that dual inhibition of HIF1α and CD73 synergistically suppresses tumor cell viability, disrupts adenosine metabolism, and impairs angiogenic and migratory signaling." (PMID 41463265, 2025). "Moreover, these erasers can act synergistically with HIF-1α, as demonstrated with ALDOA, promoting hypoxia adaptation and tumor growth." (PMID 40102715, 2025). "In addition, HIF1α and HIF2α expression was observed in PRCC‐TFE3–expressing tumor regions, which also contained many CD31‐positive cells, indicating hypervascularity." (PMID 39807625, 2025). "Thus, the synergistic interactions of survivin, HIF‐1α, and TGF‐β allow cancer cells to evade apoptosis and promote metabolic adaptations to sustain tumor growth and progression." (PMID 39535730, 2025). "HIF-1α enhances reliance on anaerobic glycolysis, further increasing LDH levels, and promotes angiogenesis (via VEGF upregulation), inhibits apoptosis (via BNIP3 regulation), and contributes to tumor stemness and invasiveness." (PMID 41229502, 2025). "In this respect, HIF-1α may induce the increased expression of VEGF, glycolytic enzymes, IGF2, and Bcl-2 genes, which facilitate the tumor cells’ adaptation to the hypoxic tumor microenvironment, by stem cells’ survival." (PMID 40227577, 2025). "Panobinostat (LBH589) has been shown to disrupt the heat shock protein 90 (Hsp90)/HDAC6 complex and induce degradation of hypoxia-inducible factor 1α (HIF-1α), resulting in decreased vascular endothelial growth factor (VEGF) expression and subsequent inhibition of tumor angiogenesis and growth." (PMID 40450300, 2025). "Tumor-derived exosomes (TDEs) carry various bioactive molecules, including TGF-β, caveolin-1, HIF-1α, and β-catenin, which collectively enhance the invasive and migratory capabilities of recipient cells, promote immune evasion, and contribute to drug resistance." (PMID 40630801, 2025). "HIF-1α and HIF-2α are widely overexpressed in multiple tumor types." (PMID 41583457, 2025). "STAT3 activation induces the expression of hypoxia-inducible factor 1-alpha (HIF-1α) and vascular endothelial growth factor (VEGF) in tumor cells, while VEGF, in turn, activates STAT3 in endothelial cells, establishing a feed-forward loop that sustains angiogenesis." (PMID 40299416, 2025).
tumor (continued). "This review highlights the central importance of ROS-regulated signaling pathways—including MAPK/ERK, PI3K/Akt/mTOR, JAK/STAT, NF-κB, HIF-1α, and NRF2—in driving proliferation, survival, metabolic adaptation, immune evasion, and therapy resistance in tumor cells." (PMID 40867898, 2025). "HIF1α upregulates the vascular endothelial growth factor (VEGF) and platelet-derived growth factor (PDGF) to induce angiogenesis in the TME as well as inducing glucose transporters GLUT1 and GLUT3 to enhance tumor cell glycolytic metabolism." (PMID 41614767, 2025). "Persistent HIF-1α stabilization in malignancies arises from the accumulation of genetic lesions (e.g., VHL deletion) or reactive oxygen species (ROS) under normoxia, compounded by tumor vascular abnormalities inducing regional hypoxia." (PMID 41181157, 2025). "Additionally, upregulation of HIF-1a and HIF-2a was evident in radioresistant PCa cells and recurrent tumors following RT, suggesting hypoxic conditions within the tumor microenvironment." (PMID 40282462, 2025). "In these factors, like Interferon Regulatory Factor 1 (IRF1) and Nuclear factor, erythroid 2 like 2 (NFE2L2) have been reported to function in the anti-tumor capacity, while HIF-1 alpha (HIF1A) and Signal transducer and activator of transcription 3 (STAT3) to support tumor growth and immune evasion." (PMID 40230843, 2025). "HIF-1α activation in hypoxic regions induces IL-6 secretion, which in turn stimulates FPN expression in macrophages, enhancing iron export and availability to tumor cells." (PMID 40861444, 2025). "Notably, in HIN and LIN, the coefficient correlation of UBE2S, HIF‐1α, and FOXM1 increased as an increase in tumor grade." (PMID 41427004, 2025). "In the tumor microenvironment, where hypoxia and hypercapnia coexist, hypercapnia could potentially attenuate hypoxia-induced HIF-α expression, counter-regulating HIF-1α and HIF-2α activity, and influence tumor cell metabolism/chemoresistance." (PMID 39914740, 2025). "We hypothesize that dual targeting of HIF1α and CD73 will synergistically reduce EAC cell viability and disrupt pro-tumor microenvironmental pathways, offering a novel therapeutic approach for hypoxic, treatment-resistant EAC." (PMID 41463265, 2025). "Moreover, succinate released by tumor cells activates succinate receptor 1, driving TAM education toward the M2 phenotype through the succinate receptor 1-PI3K/HIF-1α pathway." (PMID 41019982, 2025). "In tumor cells TRAP1 down-regulates SDH activity, installing a pseudo-hypoxic condition sustained by succinate-dependent stabilization of the transcription factor HIF-1α." (PMID 40877908, 2025). "According to reports, the rapid proliferation of tumors leads to hypoxia in the tumor microenvironment (TME), which activates the activity of HIF-1α, the crucial transcriptional factor that helps upregulate cancer-associated proteins and promote tumor progression." (PMID 40775462, 2025). "While this “vascular shutdown” effectively starves tumors, surviving hypoxic cells at the tumor periphery often upregulate pro-angiogenic factors (e.g., VEGF, HIF-1α) and adopt aggressive metabolic phenotypes (e.g., enhanced glycolysis, lactate shuttling), driving recurrence and metastasis." (PMID 40235732, 2025). "Tumor growth significantly decreased by approximately threefold upon HIF-1α knockdown, with no further reduction observed with ERCC6L knockdown in HIF-1α-depleted xenografts, suggesting convergence of ERCC6L and HIF-1α mechanisms in this context." (PMID 40691138, 2025). "Therapeutic strategies that mimic normoxic conditions can facilitate HIF1α degradation and restore the TCA cycle, thus reducing the reliance of GBM hypoxic cells on glycolysis, impairing their survival in the oxygen-deprived tumor core." (PMID 39859381, 2025).
tumor (continued). "Additionally, research on SGLT-2 inhibitor drugs shows that they exert anti-tumor effects by modulating the AMPK/mTOR and HIF-1α pathways, providing a new perspective on the overlap between pathways in metabolic diseases and cancer." (PMID 41460830, 2025). "Pathway analysis, which included all genes associated with the HIF1A pathway according to the Kyoto Encyclopedia of Genes and Genomes (KEGG) revealed no significant changes in pathway expression in tumor and before and after treatment with metformin." (PMID 40468055, 2025). "iNOS is frequently upregulated in the tumor microenvironment, driven by inflammatory cytokines such as IL-6 and TNF-α, as well as hypoxic conditions that activate transcription factors like hypoxia-inducible factor-1 alpha (HIF-1α)." (PMID 39940974, 2025). "The hypoxia–HIF1α axis may further reinforce this program, as HIF1α induces xCT in OSA cells, enhances CSPG4 expression, and upregulates TLR2 in tumor and immune cells." (PMID 41375047, 2025). "TGF-β, HIF-1α, and miRNAs form a complex feedback loop, where TGF-β can induce the expression of miRNAs that negatively regulate HIF-1α, while HIF-1α can influence TGF-β signaling and miRNA synthesis, creating a dynamic balance that contributes to cellular plasticity and tumor progression." (PMID 40943648, 2025). "Similarly, anti-VEGF therapies, such as bevacizumab, have been observed to raise the expression of HIF-1α and SDF-1α, contributing to the tumor’s ability to evade treatment." (PMID 40867316, 2025). "This leads to HIF1α-induced enzalutamide resistance which can be delayed or reverted by clorgyline, the nonselective MAO inhibitor phenelzine or MAO-A silencing, further limiting tumor growth in in vivo models." (PMID 39714760, 2025). "Notably, FAP exhibited a positive correlation (r ≈ 0.4, p < 0.01) with genes involved in angiogenesis and tumor microenvironment remodeling, including VEGFA, HIF1α, and EGFR." (PMID 40430845, 2025). "Additionally, HIF-1α directly regulates key angiogenic genes, including VEGFR1 and VEGF-A, further enhancing angiogenesis and increasing tumour cell invasiveness." (PMID 40630800, 2025). "HIF-1α downregulates activating ligands, like MICA and MICB, on tumor cells through MMP-mediated shedding and suppresses the expression levels of critical NK activation markers, including NKG2D, NKp30, NKp44, and NKp46, resulting in reduced NK cell cytotoxicity." (PMID 41511303, 2025). "The downregulation of p-PI3K and p-AKT confirms suppression of survival signaling, while the inhibition of key oncogenic regulators AKT1, MTOR, HIF1A, SRC, and ESR1 suggests broader effects on tumor metabolism, hypoxia adaptation, and growth factor receptor pathways." (PMID 40746726, 2025). "Moreover, HIF-1α is activated in hypoxic environments, promoting the expression of VEGF, which further facilitates tumor vascularization to meet the oxygen and nutrient demands of tumor cells." (PMID 40438141, 2025). "For instance, some NPs and TCMs exert anti-VM effects by regulating the expression of key VM-related molecules such as VE-cadherin, EphA2, and HIF-1α; inhibiting signaling pathways including PI3K/Akt and Wnt/β-catenin; suppressing EMT; and destroying the stemness characteristics of tumor cells." (PMID 41019994, 2025). "Upon stabilisation, HIF-1α induces a suite of genes involved in angiogenesis (VEGF, ANGPT2, SDF1, and SCF), glucose metabolism (GLUT1), and invasion (MMPs), all of which are crucial to tumour progression and metastatic competence." (PMID 40806577, 2025). "This means that through inhibition of HIF-1α and VEGF, VH032 may reverse or slow down these tumor-related processes." (PMID 41030787, 2025). "Specifically, the average tumor weight at the experimental endpoint was 1.96 g in the CpG control group, whereas it was reduced to 1.14 g in the TOP2A group, 1.58 g in the IGF-1R group, 1.47 g in the HIF-1α group, and 0.32 g in the TNBCvax group (p<0.001)." (PMID 40969744, 2025).
tumor (continued). "And in hypoxic tumor models, apigenin overcomes paclitaxel resistance by suppressing AKT and heat shock protein 90 (HSP90) signaling, which hinders the production of hypoxia-inducible factor-1α (HIF-1α)." (PMID 40490812, 2025). "An increase in lactate content in the tumor environment significantly increased the occupancy of HIF1A DNA by H3K18la in PC‐3 cells and increased the expression of HIF‐1α and HIF1α‐mediated PD‐L1 while limiting the expression of Sema3A in PCa cells and promoting angiogenesis." (PMID 40599233, 2025). "This may be due to the increased tumor vascular density, where endothelial cells upregulate APP expression in response to hypoxic microenvironment and pro-angiogenic signals, such as HIF-1α and VEGF." (PMID 41561750, 2025). "Additionally, in cases with a poor prognosis, HIF1A-driven pathways, such as PI3K/AKT, TNF-α, and Wnt, promote tumour proliferation and survival by metabolic reprogramming, as well as upregulation of metastasis-promoting genes such as MMP1, TWIST2, and ITGB1." (PMID 41007296, 2025). "Additionally, LMF exerts anti‐angiogenic effects by downregulating hypoxia‐inducible factor‐1α (HIF‐1α) and vascular endothelial growth factor (VEGF), thereby restricting neovascularisation and nutrient supply to the tumour microenvironment." (PMID 40960276, 2025). "Furthermore, HIF-1α can promote exosome release by transactivating RAB22A, which facilitates intercellular communication within the tumor microenvironment." (PMID 40813760, 2025). "Furthermore, lactate produced by tumor cells has been shown to enhance the expression of genes such as VEGFA and Arg1 via HIF-1α, thereby promoting M2 macrophage polarization." (PMID 40129528, 2025). "Elevated levels of HIF-1α drive the transcription of genes involved in VEGF signaling and glucose metabolism, thereby facilitating angiogenesis and glycolysis, which contribute to tumor invasion, metastasis, and resistance to RT." (PMID 40724808, 2025). "We hypothesize that DEB-TACE-induced THID may be associated with hypoxia and ischemia, which can promote metastasis by upregulating HIF-1α and VEGF, enhancing angiogenesis and tumor cell invasiveness." (PMID 40750947, 2025). "Additionally, we assessed the effects of DMF in the presence of inhibitors for HIF-1α, p300, and PKM2 on T cell-mediated tumor cell killing." (PMID 40461489, 2025). "ROS-mediated stabilization of HIF-1α promotes the expression of genes involved in glycolysis (e.g., GLUT1, LDHA), angiogenesis (VEGF), and pH regulation (CA9), thereby supporting tumor growth, metabolic reprogramming, and survival under adverse conditions." (PMID 40867898, 2025). "Subcutaneous transplantation into C57BL/6 mice yielded no important difference in tumor size between Acvr2a-KO and Acvr2a/Hif1a-KO Hepa1-6 cells." (PMID 40139191, 2025). "Moreover, hypoxic conditions in TME stimulate tumor aggressiveness driven by CXCR4, due to hypoxia-inducible factor 1 alpha (HIF1α) stabilization of CXCR4 expression and tumor cell survival in nutrient deprivations." (PMID 41383468, 2025). "Hypoxia, through HIF-1α-driven downregulation of STX11 and SYT7, was also found to promote HCC to secrete sEVs containing GPC3, which significantly contributes to inducing cell migration and EMT, as well as tumor growth in mice." (PMID 39023664, 2025). "Instead, HIF-1α might transcriptionally regulate specific kinases that influence TPM4-F-actin binding, thereby promoting tumor cell motility." (PMID 40740237, 2025).
tumor (continued). "HIF-1α also regulates the transcription of other molecules, such as vascular endothelial growth factor (VEGF) and carbonic anhydrase IX, which have also been studied in relation to tumor grade and overall survival." (PMID 40563757, 2025). "Meanwhile, Enadenotucirev (EnAd), a chimeric adenovirus, takes a different approach by downregulating HIF-1α during late-stage infection, thereby reducing VEGF and other pro-angiogenic factors, disrupting tumor vasculature, and enhancing T-cell infiltration into hypoxic regions." (PMID 41313526, 2025). "HIF-1α triggers the production of pro-angiogenic factors like VEGF, promoting new blood vessel formation, as well as transcription activation of TGF-β3 and epidermal growth factor (EGF) to facilitate tumor metastasis to oxygen-rich tissues." (PMID 39735667, 2025). "In some tumors, the expression of HIF-1α in tumors is often not entirely dependent on the hypoxia level of the tumor, but is more likely to be related to the malignancy of the tumor." (PMID 40809031, 2025). "Under hypoxic conditions, the accumulation of hypoxia‐inducible factor 1α (HIF‐1α) promotes the expression of carbonic anhydrase 9 (CA9), a member of the carbonic anhydrase family, which selectively expresses on the surface of tumor cells and gastrointestinal epithelial cells." (PMID 40873634, 2025). "Although HIF-1α and HIF-2α promote angiogenesis under oxidative stress, their contributions may diverge depending on tumor type and microenvironmental conditions." (PMID 40801639, 2025). "In addition, the expression of pro-tumor indicators in macrophages (VEGF, MMP9, TGF-β, and HIF-1α) was also higher in S100a4-OE MH-S." (PMID 40658605, 2025). "A study demonstrated that HIF1α is highly expressed in GBM cells, further promoting epithelial-mesenchymal transition (EMT), tumor invasion, and chemotherapy resistance, thereby exacerbating tumor malignancy." (PMID 40290443, 2025). "S2, HIF-1α signal intensity exhibited a positive correlation with both Gr-1 and CD133 expression, demonstrating significantly enhanced CSC and MDSC infiltration within hypoxic tumor compartments compared to normoxic regions." (PMID 40901943, 2025). "There is also a relationship between the HIF-1α/MMP14 pathway, which increases tumor invasion." (PMID 40649790, 2025). "Understanding the regulatory nodes of the Warburg effect, such as HIF-1α and LDHA, may provide new avenues for therapeutic interventions aimed at halting tumor progression and restoring immune function 17, 30-32." (PMID 41281744, 2025). "Moreover, the inhibitory effect on the VHL/HIF-1α/VEGF signaling pathway was confirmed, supporting its role in reducing tumour growth." (PMID 41030787, 2025). "It has been found in GBM that glucose transporter type 1 (GLUT1), HIF-1α, lactate dehydrogenase (LDH), and MCT4 were significantly expressed in the interior region of the tumor, whereas MCT1, C-MYC, and nuclear respiratory factor 1 (NRF1) were significantly expressed in the lateral region." (PMID 41450919, 2025). "Additionally, evaluating oxygen gradients within spheroids and validating hypoxic regions through immunostaining for hypoxia-inducible factor-1α (HIF-1α) and carbonic anhydrase IX (CAIX) would provide insights into the tumor microenvironment." (PMID 40943584, 2025). "Notably, hypoxia also decreases HIF-1α degradation and upregulates the PD-L1 expression in the TME, thus facilitating tumor immunoevasion." (PMID 39776799, 2025). "Additionally, PTTG1 influences angiogenesis by regulating VEGF expression through HIF-1α and the PI3K/AKT/mTOR pathway, thereby enhancing CSC survival and tumor progression." (PMID 40072059, 2025).